TRAV8-6 (T cell receptor alpha variable 8-6)
Description:
V region of the variable domain of T cell receptor (TR) alpha chain that participates in the antigen recognition. Alpha-beta T cell receptors are antigen specific receptors which are essential to the immune response and are present on the cell surface of T lymphocytes. Recognize peptide-major histocompatibility (MH) (pMH) complexes that are displayed by antigen presenting cells (APC), a prerequisite for efficient T cell adaptive immunity against pathogens. Binding of alpha-beta TR to pMH complex initiates TR-CD3 clustering on the cell surface and intracellular activation of LCK that phosphorylates the ITAM motifs of CD3G, CD3D, CD3E and CD247 enabling the recruitment of ZAP70. In turn ZAP70 phosphorylates LAT, which recruits numerous signaling molecules to form the LAT signalosome. The LAT signalosome propagates signal branching to three major signaling pathways, the calcium, the mitogen-activated protein kinase (MAPK) kinase and the nuclear factor NF-kappa-B (NF-kB) pathways, leading to the mobilization of transcription factors that are critical for gene expression and essential for T cell growth and differentiation. The T cell repertoire is generated in the thymus, by V-(D)-J rearrangement. This repertoire is then shaped by intrathymic selection events to generate a peripheral T cell pool of self-MH restricted, non-autoaggressive T cells. Post-thymic interaction of alpha-beta TR with the pMH complexes shapes TR structural and functional avidity.
Synonyms: TCRAV1S3; TCRAV8S6; TRAV86
Gene: T-cell receptor variable (V) gene on chromosome 14 (21,978,459 to 21,979,120, forward strand). Ensembl gene ENSG00000211795.
Subcellular location: Cell membrane
Gene Ontology:
Biological process: adaptive immune response
Cellular component: immunoglobulin complex; plasma membrane
Homologues: Orthologues: macaque TRAV8-6 (76% identical). Paralogues in human: TRAV8-4 (80% identical), TRAV8-2 (77% identical), TRAV8-3 (65% identical), TRAV8-1 (64% identical), TRAV8-7 (61% identical), TRAV3 (58% identical), TRAV16 (52% identical).